CXCL2 (C-X-C motif chemokine ligand 2)
Diseases named in the same sentence as CXCL2 in open-access papers (continued):
Sharing a sentence is not in itself a finding about the gene and the disease.
tumor (continued). "After chemotherapy, neutrophils are recruited via tumor cell-secreted CXCL1 and CXCL2 signaling to the liver, where chemotherapy increases the expression of growth arrest specific 6 (Gas6) in circulating neutrophils." (PMID 38982491, 2024). "CCL5, CXCL1, CXCL2, CXCL5, and CXCL12 are chemokines produced by senescent cells that have opposite effects on tumor development." (PMID 39007138, 2024). "We identified pro-inflammatory cytokines (IL1A, IL1B, IL6), and chemokines (CCL3, CXCL2, CXCL3) that promote inflammation-promoted neoplasia." (PMID 38529274, 2024). "Activation of lung epithelial TLR3 by RNAs in tumor-derived exosomes via NF-kB and MAPK pathways increased the production of chemokines such as CXCL1, CXCL2, CXCL5, and CXCL12, leading to the recruitment and accumulation of neutrophils for PMN formation." (PMID 38495881, 2024). "Exosomal RNA derived from tumor stem-like cells stimulates neutrophils to promote colon cancer tumorigenesis by secreting CXCL1 and CXCL2." (PMID 39100676, 2024). "TAMs and TANs can be recruited into the tumor microenvironment by chemokines produced by cancer cells, such as the chemokines signaling axis CXCL1, CXCL2, CXCL5, CXCL8–CXCR2, and CXCR1." (PMID 39769501, 2024). "IL-6, CXCL2, and CXCL12 are cytokines/chemokines that are released by CAFs to regulate tumor immunity and angiogenesis." (PMID 39001545, 2024). "Studies have shown that tumor necrosis factor-α activated CXCR2 ligands (CXCL1, CXCL2 and CXCL5) expressed by MSCs can effectively aggregate and migrate CXCR2+ neutrophils into tumor and significantly promote tumor metastasis." (PMID 39679363, 2024). "When methylation levels were analyzed against clinical outcomes, we found 4 CpG sites around CXCL2, 16 CpG sites around CXCL12, and 3 CpG sites around CXCL14/17 where altered methylation appeared to affect tumor behavior and patients’ outcomes." (PMID 38232115, 2024). "The immune genes CXCL1, CXCL2, IL1B, IL6, CXCL8, PTGS2, and SPP1 demonstrated elevated expression levels in tumor tissue (TU) relative to all other tissues, thus validating the results obtained from the NanoString analysis (Supplementary 1)." (PMID 38979413, 2024). "NF-κB plays an important role in CAFs, mediating the upregulation of proteases such as COX2, CXCL1, CXCL2, CYR61/CCN1, IL-1β, IL-6, and osteopontin, thus promote tumor growth, recruit macrophages, and form tumor vasculature." (PMID 39146202, 2024). "RT-qPCR results showed increased expression of CXCL2, CXCL3, and CXCL5 in tumor tissues after MC-LR exposure." (PMID 39273011, 2024). "The chemokines that are highly expressed in the TME of glioblastoma have been characterized by CXCL2, IL-8, and CCL2, which can promote tumor invasion via facilitating cell proliferation, tumor growth, and angiogenesis." (PMID 39061427, 2024). "ACKR1 on the surface of endothelial cells binds, clears and regulates various chemokines such as CXCL1, CXCL2, CCL13 and CCL18, which play key roles in angiogenesis and tumour progression." (PMID 39601163, 2024). "CXCL2 is also part of the ELR+ CXC chemokines, acting as a potent attractant of neutrophils and shown to be responsible for TAN infiltration in multiple tumor types." (PMID 38339310, 2024). "The expression levels of CXCL1, CXCL2, and CXCL8 were significantly elevated, showing a more than threefold increase in over 80% of the analyzed tumor samples." (PMID 38979413, 2024). "Consistently, under the stimulation of heat-killed P. intermedia in our study, the glutamatergic system was downregulated, while the expression levels of CXCL1, CXCL2, and CXCR2 increased and Tregs accumulated in tumor tissues, resulting in tumor progression." (PMID 38515216, 2024). "Neutrophils are recruited to the PDAC TME via multiple tumour-secreted chemokines including CXCL1, CXCL2, CXCL5, and CXCL8." (PMID 38384463, 2024).
tumor (continued). "IL-17A produced by neutrophils exacerbates tumor growth by inducing CXC chemokines (CXCL1, CXCL2, CXCL3, CXCL5, CXCL8, and CXCL11) in gastric cancer cells to recruit neutrophils to the invasive edge." (PMID 39906741, 2024). "The recruitment of tumor-associated macrophages (TAMs) to tumor sites is mediated by chemokines such as CCL2, CCL5, CCL7, CXCL1, CXCL2, and CXCL4, which promote tumor survival." (PMID 39769501, 2024). "In Pten‐null senescent tumours, the JAK2/STAT3 pathway was activated, resulting in the secretion of CXCL1, CXCL2 and IL‐6, thereby promoting macrophage M2 polarisation." (PMID 39270064, 2024). "Secreted CXCL2, upon binding to CXCR2 on the surface of M2-type macrophages, facilitated the infiltration of these immune cells into the tumor center." (PMID 38605400, 2024). "Snail-expressing tumor cells increased Cxcl2 secretion from neutrophils in the TME, thus accelerating pro-tumor neutrophil infiltration and tumor progression." (PMID 39061147, 2024). "By RT-qPCR, we revalidated the expression of CXCLs (CXCL2, CXCL3, CXCL5, CXCL10) in MB49 YAP1-Sh clones and tumor tissues from VP-treated mice bearing UCB cell–derived xenografts." (PMID 39630608, 2024). "CXCR2-positive MDSCs are recruited into the tumor microenvironment via chemokines CXCL1 and CXCL2 mainly expressed in tumor colonic epithelial cells, which is critical for colitis-associated tumor formation and progression." (PMID 37124519, 2023). "Both CXCL1 and CXCL2 are ligands of CXCR2, which promotes tumor growth and progression by inhibiting the cytotoxic activity of CD8+ T cells." (PMID 36713833, 2023). "Neutrophils are recruited to the tumor (site of injury) through secretion of inflammatory cytokines such as tumor growth factor β (TGFβ), CXCL8 (also known as IL-8), CXCL1, CXCL2 as well as IFNs." (PMID 36910138, 2023). "CXCL2 and CXCL5 negatively correlated with proliferation, angiogenesis, recruitment of MDSCs, and positively correlated with tumor infiltration by NK cells." (PMID 37686093, 2023). "Irradiation caused the release of γH2AX (a marker of DNA damage), followed by elevated levels of chemokines CXCL1, CXCL2 and CCL5 to recruit TANs to the tumor site." (PMID 37833255, 2023). "Major initiators of tumor inflammation such as CCL2, CXCL1, CXCL2, CXCL11, CSF1, LTB, and TNFSF10 were found to increase in both cell lines, while inflammation suppressors like IL13and IL1RN were decreased." (PMID 36831395, 2023). "The abundances of CXCL1, CXCL2, and CXCL5 in the lungs of C57 mice with EO771 tumor were 38.0-fold, 19.6-fold, and 10.8-fold, respectively, higher than that in the lungs of BALB/c mice with 4T1 cancer." (PMID 37553342, 2023). "In MC-38 tumor grafts, using the same experimental set-up as in RM-9, radiation increased mRNA levels of CXCL1, CXCL2, CXCL3, and CXCL5 at 24 h post-treatment and protein levels of CXCL5 at 24 h and 48 h post-treatment." (PMID 38067390, 2023). "In their study, worse tumor features and poor overall survival in patients with CRC were influenced by CXCL1, CXCL2, CXCL8 and CXCL13, which contributed to CRC treatments." (PMID 37393391, 2023). "The levels of cytokines CCL21, eotaxin, CXCL1, CXCL2, CCL7, CCL19, and CCL25, which are capable of supporting tumor invasion, were reduced in CM from MSCs-TRAIL by 1.2, 1.3, 4-8, 3.4-1.3, 1.5, and 1.3 times, respectively (n = 3, ** p < 0.01)." (PMID 36661524, 2023). "Here, by secretome analysis of hepatocyte and liver cancer cell lines, we identify a secreted tumor suppressor, PRSS35, that inhibits HCC progression through cleavage of the chemokine CXCL2, which mediates pro-tumor neutrophil function." (PMID 36934105, 2023). "Once differentiated, MDSCs reach the tumor through the guide of chemoattractive molecules, such as CXCL5 and CXCL2." (PMID 36980187, 2023).
tumor (continued). "As detected by qPCR, significantly increased mRNA expression levels of CXCL1, CXCL2, CCL5, CXCL10, and IFN-β were detected in tumor tissues isolated from the shIDH3α + CDDP + PD-L1 group compared to the control+CDDP+PD-L1 and shIDH3α groups." (PMID 36980689, 2023). "CXCR2 ligands, including CXCL5, CXCL2, and CXCL1, produced by TNF-α activated MSCs account for the deposition of neutrophils at tumor primary sites and contribute to the metastatic microenvironment formation." (PMID 38022534, 2023). "Three neutrophil chemokines, CXCL1, CXCL2, and CXCL8 were all found upregulated in the tumor compartment of responders." (PMID 37835599, 2023). "Many stimuli have been reported in previous literature, including IFN-γ and GM-CSF, which induce neutrophils to N1 polarization for anti-tumor function, and IL-6, IL-8, CXCL2, and CXCL5, which induce neutrophils to N2 polarization for pro-tumor function." (PMID 37063892, 2023). "We measured the expression of CXCL-1 and CXCL-2 in the tumor tissue and detected higher expression of CXCL-1 in Kyse-410 than Kyse-30 tumors while the expression of CXCL-2 was below the detection limit for both tumors." (PMID 37046658, 2023). "CHI3L1 also induces the expression of pro-tumorigenic molecules, including CXCL2, MMP-2, and MMP-9, which contribute to tumor growth and proliferation." (PMID 37480002, 2023). "Neutrophil cluster 6 also has high expression of Ccl2, Ccl3, Ccl4, Ccl5, and Cxcl2, which are inflammatory mediators involved in MDSC migration to and activation in the tumor microenvironment." (PMID 37483625, 2023). "After stopping gemcitabine treatment, metastatic tumor cells secrete CXCL1 and CXCL2 to attract neutrophils that express growth arrest-specific 6 (Gas6) protein, a ligand of AXL receptor on metastatic tumor cells, resulting in tumor regrowth and progression." (PMID 37173915, 2023). "As the murine orthologs of human GRO-α (CXCL1) and GRO-β (CXCL2) are often studied instead of IL-8, we determined the expression of these chemokines in ESCC tumor bearing mice." (PMID 37046658, 2023). "CXC (such as CXCL1, CXCL2, CXCL5, CXCL6, and CXCL8) at the tumor site involve CXCR2+ neutrophils that differentiate into TANs." (PMID 36980182, 2023). "We previously demonstrated that SNAIL secreted a large amount of CXCL2 to attract M2 macrophages by affecting EMT, which promoted the migration and proliferation of tumour cells." (PMID 35541899, 2022). "NF-κB-mediated chemokine secretion bridges tumor cells and cells in the TME, and CXCR2 ligands (CXCL2 and CXCL3) enhance MDSC chemotaxis in advanced PCa9,16,18." (PMID 36435834, 2022). "Recruitment of circulating neutrophils in tumor tissues is mainly regulated by CXCL1, CXCL2, CXCL8 and CXCL5 chemokines, the complement component anaphylatoxin C5a and tumor-derived oxysterols." (PMID 35158779, 2022). "According to several genomic selection strategies, CXCL2, a ferroptosis-related gene, was found to be down-regulated in HCC and influence tumor progression and clinical prognosis of HCC patients." (PMID 36276119, 2022). "In HT-29 and HCT116 CRC cells, tumor growth and angiogenesis was promoted by guanine the nucleotide-binding protein alpha-13 (GNA13) via upregulation of CXCL2 through the activation of the PLC-DAG-PKC-NF-kB signaling pathway." (PMID 35954156, 2022). "CXCL2 binds to CXCR2, which in turn couples with Gαi to stimulate neutrophil chemotaxis and endothelial cell migration for tumor transformation and growth in CRC cells." (PMID 35954156, 2022). "MMP9_macro expressed genes related to inflammatory chemokines (CXCL2, CXCL3, CXCL8) and genes like MMPs (MMP19, MMP9), which play an important role in tumor tissue remodeling." (PMID 35935940, 2022). "Remarkably, we observed clear induction in the expression of marker genes of inflammatory progenitor cells after treatment with tumor cell-conditioned medium, including CCL2, CXCL2, TNFAIP6, and TNFRSFL12a." (PMID 36376273, 2022).
tumor (continued). "Several chemokines (CCL2, CXCL1, CXCL2, CXCL10) were also increased in MC38 and CT26-conditioned media and tumor-bearing mouse serum." (PMID 35962398, 2022). "In melanoma tumor, the level of CXCL1, CXCL2, and CXCL3 is significantly elevated, accompanied by proangiogenic activity." (PMID 36612163, 2022). "Our study found that SNAIL induced the continuous secretion of CXCL2 by promoting the occurrence of EMT, which promoted the enrichment of immunosuppressed macrophages and mediated the immune escape of tumour cells." (PMID 35541899, 2022). "Many effector cells then travel through the bloodstream to the tumor site by involving various chemokines (e.g., C-C motif chemokine ligand 2 (CCL2), C-X-C motif chemokine ligand 2 (CXCL2), and C-X-C motif chemokine ligand 16 (CXCL16))." (PMID 35456701, 2022). "CD163+ TAMs produced tumor-supporting cytokines (IL-6 and CXCL2) activated STAT3 in tumor cells and supported tumor progression." (PMID 36686729, 2022). "In contrast, a TEC subpopulation expressing CXCL2, IL-6 and ACKR3 was markedly suppressed in tumor with only marginal increase after chemotherapy." (PMID 36253784, 2022). "Compared to fibroblasts from normal tissues, the top upregulated genes in tumor-derived fibroblasts were CXCL8, CXCL2, CCL2, CXCL3 and CXCL1, and the top downregulated genes were IGFBP5, PTGDS, CCN5, CFD, and RAMP1." (PMID 36357663, 2022). "Neutrophil-attracting chemokines, such as CXCL1, CXCL2, or CXCL8, are induced in hypoxic tumor tissue, through the activation of hypoxia-inducible factor 1 (HIF-1α or β), and support neutrophil migration to the tumor site via CXCR1 and CXCR2 receptors." (PMID 35158807, 2022). "Cytokines CXCL1, CXCL2, and CXCL8 in Cancer Cells interact with CXCR1 and CXCR2 in Neutrophils, chemotactic the activity of Neutrophils, and promote the generation of tumor immune microenvironment." (PMID 36401283, 2022). "The activation of Stat3 induced the secretion of glutamic acid-leucine-arginine (ELR) motif CXCLs (CXCL1, CXCL2, CXCL3 and CXCL8) in tumor cells." (PMID 35280694, 2022). "Once they reach the tumor site, TANs secrete a vast set of factors potentially involved in the biology of CCA (such as MMP-8, MMP-9, CXCL1, CXCL2, CXCL6, CXCL8, CCL7, and VEGF)." (PMID 39301518, 2022). "In other reports, CXCL2 dose-dependently increases the expression of VEGF within the angiogenic front of tumor margins, thereby promoting tumor angiogenesis, tumor growth and hepatic metastasis in the CXCR2-expressing CT26 CRC cell-induced CRC mice." (PMID 35954156, 2022). "The COX-2/PGE2 pathway induces IL-11, chemokine (C-X-C motif) ligand CXCL-1, CXCL-2, and CXCL-5, which help to promote tumor growth and maintain cancer cell stemness." (PMID 35892729, 2022). "At 72 h, colon and tumour tissue were collected and examined for histopathological changes and RT-PCR for genes of interest; TLR4, MD-2, CD-14, MyD88, IL-6, IL-6R, CXCL2, CXCR1, and CXCR2." (PMID 35962138, 2022). "The result shows that in tumor cells, PMEPA1 were negatively correlated with some chemokines (including CXCL1, CXCL11, CXCL2, CXCL8, CX3CL1) and positively correlated with CXCL14 and LAG3." (PMID 34777336, 2021). "Overall, we found expression of VEGF and the alternative proangiogenic factors CXCL2 and IL8 in human GBM samples, supporting our findings about the importance of the CXCR2 signaling pathway for tumor progression." (PMID 33807899, 2021). "Chemokines, like CXCL2, CXCL8 and CCL5, can mobilize and activate resting NK cells, resulting in tumor cell cytolysis." (PMID 34956878, 2021). "CHI3L1 can promote tumor progression by upregulation of pro‐inflammatory mediators, like CCL2, CXCL2, and MMP‐9." (PMID 33626234, 2021). "This was explained by the fact that CD14high tumor cells have a higher production of IL6, IL8/CXCL5, CXCL1, CXCL2, M-CSF, VEGF-A, FGF-2 than CD14low tumor cells." (PMID 34572939, 2021).
tumor (continued). "CXCL1 and CXCL2 chemokines strongly affect NDN and LDN migration, and tumor-conditioned media differently impact their chemotaxis." (PMID 34680231, 2021). "It accelerates tumor growth by silencing tumor suppressors and DNA repair genes, influences the activity of immune and endothelial cells via CXCL1 and CXCL2 and inactivates ERK, NF-kB and PI3K-AKT pathways resulting in increased levels of β-catenin signaling." (PMID 34944856, 2021). "Making up for 30–50%, TAMs represent a large proportion of the tumor mass and shape the tumor microenvironment by secreting chemokines, such as CXCL2 and IL8, and growth factors like VEGF and thus contribute to tumor angiogenesis that sustains tumor growth." (PMID 34681839, 2021). "For instance, it was found that the chemokines C-X-C motif ligand 1, 2, 3, and 8 (CXCL1, CXCL2, CXCL3, and CXCL8) are overexpressed in melanomas, which is accompanied by increased proliferation of tumor cells and tumor metastasis." (PMID 34885171, 2021). "In summary, recurrent GBM tumors were different to their matched primary counterpart with regard to TAM infiltration and the expression of the alternative proangiogenic molecules CXCL2 and IL8, while VEGF and the tumor vascularization remained comparable." (PMID 34681839, 2021). "Chemokines secreted in tumor microenvironment (TME), as CXCL2 and CXCL8, correlate to chemoresistance." (PMID 34038868, 2021). "IL8, CXCL2, CXCR1 and CXCR2 are expressed by various GBM tumor cell lines as well as by tumor cells and endothelial cells in GBM patients." (PMID 34203660, 2021). "There was an upregulation of IL-1b, Ltb, Tnf, and Cxcl2 in brain organoids with ZIKVBR and tumor cells indicating inflammatory signaling mediated by the TNF family." (PMID 34696533, 2021). "As we verified the angiogenic potential of CXCL2 and IL8, implying an involvement of the CXCR2 axis in tumor angiogenesis, we aimed to investigate the effect of CXCR2 antagonist SB225002 on primary human endothelial cells." (PMID 33807899, 2021). "It has been shown that certain tumours produce chemotactic agents, such as TNFα; IL‐17; CXCR2 ligands CXCL1, CXCL2, CXCL5, and CXCL6, to attract neutrophils." (PMID 33665979, 2021). "Our data show high expression of ligand in many tumor clusters, including high CXCL12 in Tr11, CXCL2 in Tr3, and CXCL16 in Tr10 with high CXCR4 receptor expression in tumor endothelial cells supporting prior reports." (PMID 34497364, 2021). "Low CXCL2, 3, and 12 mRNA levels predicted high RFS, suggesting that they play important regulatory roles in promoting tumor recurrence." (PMID 34247149, 2021). "It is well known that tumor cells or stromal cells in the tumor microenvironment secrete chemokines such as C-C motif chemokine ligand 2 (CCL2), C-X-C motif chemokine ligand 1 (CXCL1), CXCL2, and CXCL5." (PMID 34209505, 2021). "CHI3L1 up-regulates pro-inflammatory mediators, CCL2, CXCL2 and MMP-9, all of which contribute to tumor growth and metastasis, and treatment with chitin can significantly reduce these effects." (PMID 33937022, 2021). "Our results suggest that EOC cells can potentially secret CXCL2 and CXCL8 to TME that act autocrinally on tumor cells CXCR2, conferring the poor prognosis of the disease that is inferred by low patients’ OS." (PMID 34038868, 2021). "Lung epithelial cells, when exposed to tumor-derived exosomal RNAs, are also able to recruit neutrophils by secreting CXCL1, CXCL2, CXCL5, and CXCL1214." (PMID 34707103, 2021). "In cytokine and chemokine array analyses the overexpression of Lrp5 reduced the levels of several tumor-promoting factors in CM, including CXCL2, GM-CSF, IL6, LIF, DLK1 and MRP with an increase in IL27, a tumor-suppressing cytokine." (PMID 33859739, 2021). "The high expression of CXCL1/CXCL2 promoted the migration of myeloid cells and disrupted the accumulation of CD8+T cells in the tumor microenvironment, leading to accelerated tumor proliferation." (PMID 34630121, 2021).